TAF11L12 (TATA-box binding protein associated factor 11 like 12)
Gene: Protein-coding gene on chromosome 5 (17,610,392 to 17,612,111, forward strand). Ensembl gene ENSG00000249156.
Gene Ontology:
Molecular function: RNA polymerase II general transcription initiation factor activity; protein heterodimerization activity
Biological process: RNA polymerase II preinitiation complex assembly; transcription initiation at RNA polymerase II promoter
Cellular component: transcription factor TFIID complex; nucleus
Homologues: Orthologues: tropical clawed frog taf11 (48% identical), zebrafish taf11 (47% identical), Drosophila melanogaster Taf11 (43% identical), Caenorhabditis elegans taf-11.1 (36% identical), Caenorhabditis elegans taf-11.2 (30% identical). Paralogues in human: TAF11L11 (94% identical), LINC02218 (93% identical), TAF11L2 (92% identical), TAF11L13 (89% identical), TAF11L10 (88% identical), TAF11L5 (88% identical), TAF11L6 (88% identical), TAF11L7 (88% identical), TAF11L8 (88% identical), TAF11L3 (87% identical), TAF11L4 (87% identical), TAF11L9 (87% identical), and 2 more.